NBPF22P (NBPF member 22, pseudogene)
Synonyms: MGC48637
Gene: Transcribed unprocessed pseudogene on chromosome 5 (86,282,766 to 86,296,309, forward strand). Ensembl gene ENSG00000205449.
Diseases named in the same sentence as NBPF22P in open-access papers:
NBPF22P is named in the same sentence as 1 disease in open-access papers, as found by Europe PMC text mining. Sharing a sentence is not in itself a finding about the gene and the disease. The quoted sentences say what the papers report.
tumor (1 paper, 2019). "In the lncRNA group, lncRNA-TOB2P1, LOC100499489, lnc-NMRAL2p, and lnc-NBPF22P were markedly upregulated in tumor tissues, while LINC01093, LOC100130899, LOC200772, and lnc-FENDRR were significantly downregulated in tumor tissues, compared to the adjacent controls." (PMID 31156698, 2019).